CRP (C-reactive protein)
Diseases named in the same sentence as CRP in open-access papers (continued):
Sharing a sentence is not in itself a finding about the gene and the disease.
infection (continued). "ROC analysis demonstrated that hBD2 showed the highest detection performance for infection (AUC 0.897; p < 0.001) followed by PCT (AUC 0.576; p = ns) and CRP (AUC 0.517; p = ns)." (PMID 37296737, 2023). "Whereas in MHD patients with CRP less than 23 mg/L or CRP in the range of 23–82 mg/L with NLR below 9.7, there is about a sixfold decrease in the likelihood of infection compared to values higher than these cutoff points in the training group." (PMID 37016028, 2023). "C-reactive protein (CRP) is a clinically useful marker of systematic inflammation, and its synthesis occurs in the liver and is induced by infection and tissue injury." (PMID 36771307, 2023). "Criteria in (Section 3) Infection markers were rephrased, whereby EWS, WCC and CRP criteria qualifier wording changed from ‘is improving’ to ‘is decreasing’, ‘is trending towards the normal range’ and ‘is decreasing’, respectively." (PMID 36983089, 2023). "C-reactive protein (CRP) and procalcitonin (PCT) are broadly used to stratify infection according to disease severity and potential outcome despite their poor performance for that purpose." (PMID 37707744, 2023). "When compared to currently used biomarkers such as CRP, PCT, and IL-6, our methodology considerably reduces the time lag between the initiation of the infection and the response." (PMID 37932249, 2023). "An algorithm for the optimal CRP and NLR cutoff points for predicting infection was developed based on a decision tree analysis in the training cohort (n = 620) and then tested in the validation cohort (n = 154)." (PMID 37016028, 2023). "The Cu/Zn ratio was relatively high in infected newborns and was positively correlated with C-reactive protein (CRP) levels, and the OR for the Cu-Zn ratio was 9.067, indicating a higher probability of infection." (PMID 37917592, 2023). "C-reactive protein (CRP) is used as a monitoring indicator for acute illnesses and can quickly respond to the severity of infection, inflammation, and tissue damage." (PMID 36406928, 2022). "Following this procedure, a period of several weeks of antibiotic treatment is needed until the infection is considered cured (normalization of the ESR and CRP and healing of the surgical wound)." (PMID 36294449, 2022). "Clinically, CRP and ESR are important indicators which are commonly used to monitor and predict lumbar postoperative infection." (PMID 36684362, 2022). "In terms of infection indicators, blood WBC was 3.9±3.1 and 5.9±3.2 (P= 0.018), and CRP was 5.5±0.9 and 10.1±1.8 (P=0.031), respectively." (PMID 33974170, 2022). "Laboratory analysis for C-reactive protein (CRP), Procalcitonin (PCT) and lactate were carried out as part of the routine studies performed in patients with suspected severe infection." (PMID 35329889, 2022). "In this study, the HDLVEF group had higher initial CRP and LDH levels, while RLVEF resulted from a chronic process already present at the time of infection and was less affected." (PMID 35463197, 2022). "Production of CRP and AGP is useful in the screening of diseases, monitoring the response of treatment, and detection of incurrent infections." (PMID 36211493, 2022). "Although previous studies have attempted to utilize CRP and ESR values to evaluate infection status, results have been variable." (PMID 36112243, 2022). "In contrast to CRP, serum PCT elevations should probably trigger a more extensive infection work-up." (PMID 36295492, 2022). "Almost forty percent of children had elevated CRP or AGP concentrations, indicative of inflammatory responses to infection." (PMID 35802561, 2022). "Our results suggested that serum levels of SCD14-ST, CRP, and PCT increased after spinal surgery, and were even higher during a postoperative infection." (PMID 35648304, 2022). "We assessed the impact of infection indicated by both acute phase proteins (APP), C-reactive protein (CRP), and α-1-acid-glycoprotein (AGP), and as reported by maternal recall on the nutritional status of infants." (PMID 36211493, 2022).
infection (continued). "A new risk scoring system in active cancer patients with suspected infection consisted of six components: ECOG PS, SpO2, creatinine, total bilirubin, CRP, and lactate." (PMID 35236914, 2022). "Biomarkers such as CRP and PCT can not only serve as a guide to diagnose infection but also as a predictor to safely discharge patients." (PMID 36475186, 2022). "The authors compared postoperative C-reactive protein (CRP) and erythrocyte sedimentation rates (ESR) as well as infection rate in both groups." (PMID 36128028, 2022). "A significant increase in the CRP levels in upper UTI can help determine the anatomical location and can help in targeting effective management of the infection by anti-microbial therapy." (PMID 35915684, 2022). "After infection control, PCT and CRP decreased to normal after 2 to 3 days and 3 to 7 days, respectively." (PMID 35633256, 2022). "Correlations between CRP and SAA at visits with an autoinflammatory disease flare, disease remission and an infection were analysed separately." (PMID 36434581, 2022). "In our study, we analyzed the clinical picture of HAinfections in the context of the most frequently ordered outpatient blood tests including CRP and CBC, and the clinical manifestations of the infection." (PMID 36649001, 2022). "CRP, PCT, and ESR are clinically validated indicators that can be used to assist the diagnosis of infection." (PMID 36760236, 2022). "Inflammatory cytokines produced by various cells after inflammatory stimulation are critical components of the inflammatory response and can induce an increase in CRP and PCT at 2 and 6 h after infection, respectively." (PMID 35795627, 2022). "CRP, PCT, and neutrophil count are the traditional serological indicators for evaluating infections." (PMID 35346147, 2022). "The C-reactive protein (CRP), a well-established host immune biomarker of infection, received renewed attention after the WHO recently endorsed CRP as a screening marker in HIV-infected individuals." (PMID 35335651, 2022). "CRP is increased in response to IL-6, IL-1β and TNF-α activation during infection and systemic inflammation." (PMID 35958594, 2022). "In terms of infection indicators, blood WBC was 11.3±11.6 before treatment and 3.9±3.1 after treatment (P =0.002).CRP was 30.9±9.9 before treatment and 5.5±1.0 after treatment (P=0.0152), both of which were better than that before treatment." (PMID 33974170, 2022). "After adjusting for age, sex, comorbidities, site of infection, lymphocytes, platelets, APACHE II and SOFA score, CRP and nCD64 index were considered as independent predictors of 28-day mortality in septic patients." (PMID 35907785, 2022). "CRP and ESR are the most common laboratory indicators of inflammatory activities, but they are vulnerable to disturbance from other factors, such as infection." (PMID 36494477, 2022). "Considering these data, we analyzed the role of CRP, white blood cells, and NLR in the early diagnosis of infections in patients with LC and overt HE." (PMID 36140479, 2022). "Laboratory investigations including a C-reactive protein (CRP) level of 2.1 mg/L and erythrocyte sedimentation rate (ESR) of 12 mm/hour suggested a low likelihood of infection." (PMID 35317840, 2022). "However, CRP constitutes a rather unspecific marker of inflammation and infection, which may be elevated due to various infectiological reasons after SPKT and may therefore not be interpreted as a specific marker of IRI or indicator of pancreatic tissue injury." (PMID 35743457, 2022). "Although his presentation supported GCA, the features of elevated ESR and CRP, headache, and fever were too general to diagnose GCA exclusively, and his additional symptoms of rhinorrhea and sinus pain more likely supported infection." (PMID 35919218, 2022). "A CRP level of 120 mg/L and procalcitonin (PCT) of 13.73 ng/mL indicated a serious pathogen infection." (PMID 36211956, 2022).
infection (continued). "On the other hand, the BBT biomarkers of lactate dehydrogenase (LDH) and C-reactive protein (CRP) that indicate tissue damage and infection performed well in our first biomarker screening." (PMID 35844547, 2022). "In line with other studies, our study showed that serum blood levels of many of these biomarkers such as CRP, blood urea, total bilirubin, CRE, ALP, albumin and LDH increase significantly with infection exacerbation." (PMID 36614820, 2022). "Other research that compared different infection indexes, such as PCT and CRP, also found that the nCD64 index was a reliable marker of postoperative infection." (PMID 36522701, 2022). "C-reactive protein (CRP) is an acute-phase inflammatory protein, which has been traditionally utilized as a clinical marker of inflammation, infection, and tissue damage." (PMID 35996695, 2022). "Further, low levels of CRP in the first trimester do not exclude maternal or fetal immune activation later in pregnancy, and the low concentrations early in pregnancy might influence risk of serious infections later on." (PMID 35393396, 2022). "CRP and SAA1 are positive APPs, and their correlation has been described in different physical conditions, including infection, trauma, inflammatory reactions, and hypermetabolic diseases, including prognosis of COVID-1924–27." (PMID 36400821, 2022). "CRP, D-dimer and SAA are notable for being highly upregulated during the “acute phase response”–the body’s physiological reaction to stresses such as infection, inflammation, and trauma." (PMID 35700185, 2022). "The objective of this matched-pair analysis was to assess the role of serum C-reactive protein (CRP) and white blood cell count (WBC) in determining infection eradication and proper timing of reimplantation." (PMID 36139954, 2022). "Diagnostic criteria of PJI have been established by the Musculoskeletal Infection Society (MSIS), including serum C-reactive protein (CRP)." (PMID 35626186, 2022). "Traditional serum biomarkers such as C-reactive protein (CRP) and procalcitonin (PCT) have also been evaluated for their abilities in distinguishing IFI and other infections." (PMID 35740137, 2022). "The exact cause of the observed elevations of CRP and SAP among mothers to individuals with ASD with co-occurring ADHD is not known, but they might be caused by either genetically determined elevated levels, or in response to some environmental factor, e.g. infection." (PMID 35393396, 2022). "Whether placental infections without detectable blood stream infection affect ferritin levels is unknown, as is whether such occult infections are associated with increases in ferritin levels that are not captured by adjustment for CRP or AGP." (PMID 35619134, 2022). "Nowadays, the use of supplementary diagnostic tools such as C-reactive protein (CRP), procalcitonin, and an early warning score, could facilitate the early diagnosis of adverse events and time-sensitive interventions in surgical patients with suspected infection." (PMID 36289973, 2022). "C-reactive protein (CRP), an acute-phase inflammatory protein is primarily synthesized and stored in hepatocytes, and released in response to infection and inflammation, primarily with the stimulation of IL-6 followed by IL-1 and tumor necrosis alpha (TNF-α)." (PMID 35683357, 2022). "However, patients who developed a secondary infection stayed 3.6- to 4.1-fold longer in hospital (33 vs 8 days; p < 0.0001) and ICUs (29 vs 8 days; p < 0.0001) and had lower CRP levels (75 vs 164 mg/L; p = 0.003) than patients who did not develop a secondary infection." (PMID 35146585, 2022). "When employing elevated levels of CRP and AGP to define the infection status, the odds of having infection in the underweight infants was 3.7 times higher." (PMID 36211493, 2022).
infection (continued). "Two patients after colonoscopy met the inclusion criteria with a high fever up to 39.0 °C in 1–2 h, and the leukocytes, C-reactive protein (CRP) and procalcitonin (PCT) increased significantly with signs of infection." (PMID 35350984, 2022). "Our study illustrates that the combination of CRP and PCT is useful in differentiating IFI from bacterial blood stream infections in febrile episodes of immunocompromised children." (PMID 35740137, 2022). "Most importantly, the DNI has been reported to be a better predictor of infection and prognosis compared to traditional markers, including WBC count, ESR, and CRP." (PMID 35926065, 2022). "Clinical parameters such as routine blood test results, C-reactive protein (CRP), procalcitonin (PCT), and erythrocyte sedimentation rate (ESR) are often used to assist determination of the severity of infection." (PMID 36760236, 2022). "Inflammatory indexes such as the WBC, CRP, and PCT were used to evaluate the level of infection and remission of the disease." (PMID 36620562, 2022). "The study results suggested that patients with NGLM are more likely to produce pus than GLM, and the level of CRP was higher in patients with GLM than NGLM, after infection with C. kroppenstedtii." (PMID 35794560, 2022). "Whereas, CRP concentration levels rise to a maximum within 24–48 h following infection, AGP responds more slowly and can take up to 3–5 days to reach plateau and then remains elevated for a longer period as the CRP level declines." (PMID 36211493, 2022). "For all of these, infection biomarkers have been searched, as are the cases of procalcitonin (PCT) or C-reactive protein (CRP), among others." (PMID 35208167, 2022). "Inflammatory biomarkers, including C-reactive protein (CRP) and pro-calcitonin (PCT), are routinely utilized for the diagnosis of clinical infection." (PMID 35463642, 2022). "The blood routine assays showed evidently increased white blood cell count (mainly neutrophils), CRP, and ESR, which suggested she was in the infection phase." (PMID 36434704, 2022). "Differences in gender, infection duration, signs of severe infection, eGFR, ESR, WBC count, hs-CRP level, and HbA1c level were statistically significant among the four groups (P < 0.05)." (PMID 35320298, 2022). "However, the significantly higher CRP level of the female Chinese sturgeon than the male in summer and the increase in CRP values in the male from fall to winter suggested that the female could contract infection or inflammation in summer whereas similar problem may occur in the male in winter." (PMID 35514333, 2022). "The C-reactive protein (CRP) is an important biomarker for inflammation and infection of the human body." (PMID 35039589, 2022). "With increasing severity of the infection, higher levels of circulating cytokines and other inflammatory biomarkers like IL6, IL-1β, TNFα, C-reactive protein (CRP) and D-dimer occurs." (PMID 36590303, 2022). "Laboratory examinations revealed elevated infection indices, such as PCT 44.52 ng/mL, CRP 40.48 mg/L, white blood cell count (WBC) 17.3 × 109/L and neutrophils 95.4%." (PMID 35350984, 2022). "However, it cannot be denied that the infection might have affected CRP levels in the other cases." (PMID 35949598, 2022). "We next divided the studied cases into postoperative infection (PI) and non-infection (PN) groups based on the diagnosis of postoperative infection, and measured the serum levels of PCT, CRP, and sCD14-ST in each group." (PMID 35648304, 2022). "It is well known that CRP and PCT levels significantly rise after 12 and 6 h of infection, respectively." (PMID 35740137, 2022). "Using a synopsis of CRP, WBC, PMN, presence of sinus tract and the calprotectin results, 11 out of 14 confirmed infections were identified." (PMID 36319727, 2022).
infection (continued). "Each validated index respectively combined with classical infection indexes of PCT and CRP, and only the combination of VCAM1 had AUC‐ROC of 0.745, which was better than that of VCAM1 (p = 0.018)." (PMID 34825737, 2022). "The present study demonstrated that using the old model of classic predictive values for infection (T > 38 °C; WBC > 12,000/mm3; ESR > 20 mm/h; CRP > 10 mg/L) can be useful for discriminating between OAIs caused by K. kingae or MSSA." (PMID 36677303, 2022). "NEUT-SFL, CRP, and neutrophil count positively correlated with BSI scores, indicating that as the neutrophils increased, the infections became more severe." (PMID 35346147, 2022). "As recurrent infections are frequent in patients with CKD, interpreting changes in CRP is challenging." (PMID 34297188, 2022). "We demonstrated that the use of the CRP results and time from symptom onset could support physicians in differentiating between viral and bacterial infections by suggesting that patients with eCRPv values >4 have a 100% chance of having a bacterial source of infection." (PMID 36477474, 2022). "Compared to CRP, the PCT has a better kinetic profile, increasing within 3–6 h after the onset of infection reaching its serum peak after 6–8 h." (PMID 35741168, 2022). "Other biomarkers such as C-reactive protein (CRP), erythrocyte sediment rate (ESR) procalcitonin and CRP/albumin ratio have been reported as useful predictors of postoperative infection." (PMID 35246692, 2022). "Under non-infection conditions, PCT and CRP levels are within normal ranges and are maintained in patients at a relative equilibrium." (PMID 36189371, 2022). "Multiplexed detections of CRP, PCT, and IL-6 can fill in the blind area of single biomarker analysis and accurately diagnose the infection." (PMID 35144683, 2022). "Seven infection/inflammation-related proteins in our assay, S100A9, VIM, LGALS1, APCS, MMP9, LDHA, and CRP, were elevated in TB-PEs and the other-infectious-PEs." (PMID 35197508, 2022). "C reactive protein (CRP) value, erythrocyte sedimentation rate (ESR), and white blood cell (WBC) count are the indexes in the diagnosis of inflammation and infections." (PMID 35752831, 2022). "We investigated the delta (∆) change in CRP and WBC values prior to both stages of two-stage revision arthroplasty as a useful marker of infection eradication." (PMID 36139954, 2022). "Over and above that, WMC-MDP is capable of rapid, robust, accurate and multiplexed analysis of CRP, PCT, and IL-6 in the dynamic battlefield environment for reliably identifying infections." (PMID 35144683, 2022). "LTBI values for both CRP and A/G ratios remained at similar levels to that of pre-infection, whereas in animals with ATB, there were elevated levels of serum CRP and a lowered A/G ratio when compared with LTBI." (PMID 35631065, 2022). "Our results agree with those previous studies, and describe how infection with SARS-CoV-2 also increases the soluble P2X7 receptor in the plasma, which positively correlates with CRP concentration." (PMID 35663992, 2022). "Several studies have proposed C-reactive protein (CRP), procalcitonin, or the chemokine (C-C motif) ligand 2 (CCL2) as markers of infection." (PMID 36292107, 2022). "We then investigated markers of organ functions (liver, kidney, heart) and biomarkers of infection (WBC, PMNs, Procalcitonin and C-reactive protein)." (PMID 36299903, 2022). "C-reactive protein (CRP) and white blood cell count (WBC) are two commonly used serum inflammatory markers for assessing infection eradication before reimplantation." (PMID 36139954, 2022). "CRP levels can more accurately reflect the changes in infection, and the rate of the decline in the ESR is significantly slower than that in CRP levels." (PMID 36686458, 2022). "Expression levels of infection indexes, such as CD64 index, PCT, and CRP, were detected and compared." (PMID 36292098, 2022).